KRABD5 (KRAB domain containing 5)
Synonyms: KRBOX5; ZNF720
Tractability: Antibody: the Human Protein Atlas places it where antibodies can reach. PROTAC: ubiquitination databases record sites on it.
Gene: Protein-coding gene on chromosome 16 (31,713,229 to 31,794,869, forward strand). Ensembl gene ENSG00000197302.
Subcellular location (Human Protein Atlas): Cytosol; Nucleoplasm; Plasma membrane
Pathways (Reactome):
Gene expression (Transcription): Generic Transcription Pathway
Gene Ontology:
Molecular function: protein binding; DNA-binding transcription repressor activity, RNA polymerase II-specific; RNA polymerase II cis-regulatory region sequence-specific DNA binding
Biological process: negative regulation of transcription by RNA polymerase II; regulation of DNA-templated transcription
Cellular component: nucleus
Genetic constraint (gnomAD): Loss-of-function variants: 11 observed, 17.31 expected, observed/expected ratio (o/e) 0.64, 90% interval 0.4 to 1.05. The upper end of that interval is the gene's LOEUF score, 1.05, which puts it in group 4 of 6, group 1 being the genes least tolerant of losing a copy. Missense variants: 132 observed, 145.08 expected, observed/expected ratio (o/e) 0.91, 90% interval 0.79 to 1.05. Synonymous variants: 48 observed, 54.19 expected, observed/expected ratio (o/e) 0.89, 90% interval 0.7 to 1.13.
Homologues: Orthologues: zebrafish si:dkeyp-19e1.4 (1% identical). Paralogues in human: ZNF862 (37% identical).
Diseases named in the same sentence as KRABD5 in open-access papers:
KRABD5 is named in the same sentence as 2 diseases in open-access papers, as found by Europe PMC text mining. Sharing a sentence is not in itself a finding about the gene and the disease.
KRABD5 shares sentences with these, for which no sentence is quoted: breast carcinoma (1 paper); osteosarcoma (1).